GFRAL (GDNF family receptor alpha like)
Description:
Brainstem-restricted receptor for GDF15 hormone, which triggers an aversive response, characterized by nausea, vomiting, and/or loss of appetite in response to various stresses. The aversive response is both required to reduce continuing exposure to those stresses at the time of exposure and to promote avoidance behavior in the future. The GDF15-GFRAL aversive response is triggered by stresses, such as anticancer drugs (camptothecin or cisplatin), cancers or drugs such as metformin. Upon interaction with its ligand, GDF15, mediates the GDF15-induced autophosphorylation and activation of the RET tyrosine kinase receptor, leading to activation of MAPK- and AKT-signaling pathways. Ligand-binding activates GFRAL-expressing neurons localized in the area postrema and nucleus tractus solitarius of the brainstem (By similarity). The GDF15-GFRAL signal induces expression of genes involved in metabolism, such as lipid metabolism in adipose tissues.
Synonyms: C6orf144; GRAL; UNQ9356; bA360D14.1
Tractability: Antibody: UniProt places it where antibodies can reach, with high confidence; its Gene Ontology location is reachable by antibodies, with high confidence; UniProt predicts a signal peptide or a membrane-spanning region.
Target class: Membrane receptor
Gene: Protein-coding gene on chromosome 6 (55,327,469 to 55,402,493, forward strand). Ensembl gene ENSG00000187871.
Subcellular location: Cell membrane
Subcellular location (Human Protein Atlas): Nucleoplasm; Plasma membrane; Actin filaments; Focal adhesion sites
Gene Ontology:
Molecular function: glial cell-derived neurotrophic factor receptor activity; protein binding; receptor tyrosine kinase binding; signaling receptor activity
Biological process: GDF15-GFRAL signaling pathway; positive regulation of MAPK cascade; positive regulation of phosphatidylinositol 3-kinase/protein kinase B signal transduction; negative regulation of appetite; nervous system development; reduction of food intake in response to dietary excess; response to metformin
Cellular component: plasma membrane; external side of plasma membrane; receptor complex
Genetic constraint (gnomAD): Loss-of-function variants: 20 observed, 24.12 expected, observed/expected ratio (o/e) 0.83, 90% interval 0.58 to 1.21. The upper end of that interval is the gene's LOEUF score, 1.21, which puts it in group 5 of 6, group 1 being the genes least tolerant of losing a copy. Missense variants: 290 observed, 281.98 expected, observed/expected ratio (o/e) 1.03, 90% interval 0.93 to 1.13. Synonymous variants: 87 observed, 91.05 expected, observed/expected ratio (o/e) 0.96, 90% interval 0.8 to 1.14.
Homologues: Orthologues: chimpanzee GFRAL (99% identical), macaque GFRAL (93% identical), dog GFRAL (80% identical), rabbit GFRAL (77% identical), mouse Gfral (70% identical), rat Gfral (68% identical), guinea pig GFRAL (65% identical), pig GFRAL (59% identical), tropical clawed frog hcrtr2 (39% identical), Caenorhabditis elegans Y69A2AR.31 (20% identical), Drosophila melanogaster Gfrl (20% identical), zebrafish gfral (18% identical). Paralogues in human: GFRA1 (20% identical), GFRA3 (20% identical), GFRA2 (19% identical), GFRA4 (15% identical).
Diseases named in the same sentence as GFRAL in open-access papers:
GFRAL is named in the same sentence as 50 diseases in open-access papers, as found by Europe PMC text mining. Sharing a sentence is not in itself a finding about the gene and the disease. The quoted sentences say what the papers report.
Obesity (35 papers, 2018 to 2025). Accumulation of substantial excess body fat. "Our results indicated that artesunate normalises body weight both prophylactically and therapeutically, while reversing metabolic abnormalities commonly associated with obesity in a GDF15/GFRAL axis-dependent manner." (PMID 38310105, 2024). "Alternatively, obesity‐associated human‐specific changes in GDF15/GFRAL/RET complex signalling could be present, reducing its efficacy." (PMID 39907315, 2025). "Importantly, the interaction of GDF15 with its receptor GFRAL (glial cell derived neurotrophic factor receptor alpha-like) in the central nervous system is able to cause weight loss in diet-induced obesity and in other animal models of obesity via reduction of food and fat5 intake." (PMID 40820083, 2025). "Two primary strategies include GDF15 analogues as GFRAL agonists for obesity treatment and GDF15‐derived peptides as antagonists to counteract cancer‐induced cachexia and related disorders." (PMID 39907315, 2025). "Animal studies demonstrate that MT1-MMP knockout restores GFRAL expression, attenuating weight gain and food intake in obese mice, suggesting this pathway as a potential therapeutic target for obesity." (PMID 41234361, 2025). "Currently, several drugs targeting the GDF15/GFRAL axis are in clinical development for various indications, including obesity, heart failure, and cachexia." (PMID 40837873, 2025). "We further demonstrated that the anti-obesity effect of artesunate was mainly mediated by the GDF15/GFRAL signalling axis." (PMID 38310105, 2024). "Although no functional investigations were performed, a more global regulatory role of GFRAL in disorders related to food intake, such as eating disorders, anorexia/cachexia and obesity, is conceivable." (PMID 38474863, 2024). "This implies the possibility of an upregulation of GFRAL under challenging conditions, like specific developmental stages in mice and humans or obesity." (PMID 38474863, 2024). "This anti-obesity action of GDF-15 was abrogated in GFRAL gene-deleted mice, while diet-induced obesity was exacerbated in GFRAL-deficient mice." (PMID 38672115, 2024). "Recently, with the discovery of GDF15’s specific receptor glial-derived neurotrophic factor (GDNF) receptor alpha-like (GFRAL), enthusiasm is heightened in understanding this hormone’s regulation and exploring its therapeutic application in obesity treatment." (PMID 35202387, 2022). "Although being a member of TGF-β superfamily, more and more evidence showed that GDF-15 has high affinity with GDNF family receptor α-like (GFRAL), which is correlated to anti-obesity effects and energy balance." (PMID 35963873, 2022). "Deficiency in the GDF15 receptor GFRAL abolishes the adipocyte ISR-dependent preferential inhibition of HFD intake and the anti-obesity effects." (PMID 34877504, 2021). "The role of GDF-15 and its receptor GFRAL in the development and progression of obesity and T2D is well described, but the molecular mechanisms accounting for the high expression of GDF-15 in these conditions is poorly understood." (PMID 33302552, 2020). "Pioneering work by Breit’s group established that GDF15 was a potent anorectic factor in the context of cancer and identified its ability to prevent diet-induced obesity in mice long before the discovery of GFRAL." (PMID 32310257, 2020). "Growth differentiation factor-15 (GDF-15) and its receptor GFRAL are both involved in the development of obesity and insulin resistance." (PMID 33302552, 2020). "Pharmacological modulation of GFRAL signaling is the target of several drug development programs including for obesity, cachexia and other eating disorders." (PMID 33158081, 2020). "The fact that metformin exerts its regulatory effect on weight via GDF15-GFRAL-RET provides proof of principle for GFRAL agonism as a therapeutic strategy in obesity." (PMID 32310257, 2020). "Based on these data, GDF15/GFRAL signalling emerges as a promising target to treat obesity in the future." (PMID 30533221, 2018).
Obesity (continued). "It has already been suggested that an upregulation of GFRAL may occur under stress or injury, such as obesity or specific developmental stages in mice and humans." (PMID 40464681, 2025). "Inhibition of GDF15/GFRAL signalling by genetic ablation of GFRAL or tissue-specific knockdown of GDF15 abrogates the anti-obesity effect of artesunate in mice with diet-induced obesity, suggesting that artesunate controls bodyweight and appetite in a GDF15/GFRAL signalling-dependent manner." (PMID 38310105, 2024). "To further confirm whether the anti-obesity effect of artesunate is mediated by the GDF15/GFRAL axis, we quantified the percentage abundance of active c-Fos+ neurons within the AP, following a bolus intraperitoneal dose of artesunate." (PMID 38310105, 2024). "Further, it is dimerized, cleaved, and secreted as mature GDF15, being considered an essential regulator of appetite through the glial-derived neurotrophic factor receptor alpha-like (GFRAL) and present at high levels in comorbidities such as obesity and diabetes." (PMID 37408184, 2023). "Treatment of rodents fed a high-fat diet with recombinant growth differentiating factor 15 (GDF15) reduces obesity and improves glycaemic control through glial-cell-derived neurotrophic factor family receptor α-like (GFRAL)-dependent suppression of food intake." (PMID 37380764, 2023). "The third candidate is GFRAL, which is required for the anti-obesity effects of GDF-15." (PMID 38254638, 2023). "GFRAL knockout mice exacerbated diet-induced obesity and insulin resistance." (PMID 34944728, 2021). "The existence, the functional role and clinical relevance of GDF15 and its signaling through a GFRAL/RET-dependent complex in gastric cancer (GC) and other human tumors remain to be elucidated, despite the widespread recognition of obesity as an important cancer-predisposing factor." (PMID 34149933, 2021). "In this regard, GFRAL may act as both an upstream and downstream therapeutic target, with appetite suppression reducing both obesity and correlated visfatin levels, and GDF15 inhibition reducing downstream visfatin mediated pAKT." (PMID 31861872, 2019). "As present research mainly focuses on the exclusive role of GFRAL in the AP/NTS in anorexia, tumor-induced cachexia and obesity, the data on potential GDF15/GFRAL signaling in other brain areas are sparse." (PMID 38474863, 2024). "In consideration of the enormous potential of GFRAL modulators to counteract overeating and obesity, the GDF-15/GFRAL/RET pathway is the most active area for drug development in this endeavor." (PMID 32508832, 2020). "In mice, glial-derived neurotrophic factor receptor alpha-like (GFRAL) is highly expressed in the area postrema and can bind with GDF-15 directly to treat metabolic related diseases such as obesity, diabetes and anorexia/cachexia." (PMID 33201838, 2020). "Furthermore, the anti-obesity benefits of artesunate were shown to require GDF15 signaling, as gene deletion of GFRAL or cell-type-specific silencing of GDF15 abolished its metabolic effects." (PMID 40837873, 2025). "Moreover, in obesity, membrane-bound matrix metalloproteinase 14 (MT1-MMP/MMP14) inhibits GDF15 signaling by blocking GFRAL." (PMID 41234361, 2025). "Here, the authors show that artesunate, an FDA-approved treatment for severe malaria, can be repurposed for the treatment of obesity via GDF15/GFRAL signaling axis without overt side effects in mice and non-human primates." (PMID 38310105, 2024). "Knockout models established that GFRAL signalling particularly protected against diet-induced obesity, while no phenotype was observed at baseline." (PMID 30533221, 2018). "In addition, the GFRAL gene was identified in 2005, and it has not been extensively studied until recently because of its important role in the anti-obesity effect of GDF-15." (PMID 38254638, 2023).
Obesity (continued). "However, it was the identification of GFRAL, a transmembrane receptor localised to the hindbrain, as the putative target for GDF15 and mediator of its weight lowering effects in rodents that framed GDF15 as a potential anti-obesity therapy." (PMID 31801546, 2019). "The fact that it signals via a specific hindbrain receptor, GFRAL, and that mice lacking GDF15 manifest diet-induced obesity suggest that GDF15 may play a physiological role in energy balance." (PMID 30639358, 2019). "Given that GFRAL is expressed solely in hindbrain neurons but not in peripheral tissues in mice, these results suggest that exogenous GDF15 administration leads to resistance to diet-induced obesity via GFRAL-dependent anorexic action in brain." (PMID 29717162, 2018).
Anorexia (24 papers, 2018 to 2025). Lack of desire to eat (loss of appetite). "Supporting the role of the GDF‐15‐GFRAL axis in cachexia, cisplatin‐induced anorexia and muscle loss were attenuated in GFRAL knockout mice." (PMID 40343378, 2025). "GDF15 activates GFRALAP/NTS neurons and supports conditioned taste and place aversions, while the anorexia it causes can be blocked by a monoclonal antibody directed at GFRAL or by disrupting CCK neuronal signalling." (PMID 32723474, 2020). "To some extent, these results are as predicted, as we and others have already reported that GFRAL expression overlaps with CCK10 and that artificial activation of CCKAP/NTS neurons causes both anorexia and CTA35,36." (PMID 39737892, 2024). "On the other hand, pancreas carcinoma and pancreatitis are strongly associated with nausea, reduced food intake and anorexia/cachexia, and are obviously mediated by the GDF15/GFRAL brainstem pathway." (PMID 38474863, 2024). "The GDF-15 has been shown to signal through the glial cell-derived neurotrophic factor (GDNF) family receptor α-like (GFRAL), which is solely expressed in the human brain stem and is associated with GDF-15-mediated anorexia and cachexia." (PMID 37905271, 2023). "In other cachexia models, GDF-15 is capable of inducing anorexia through the activation of GFRAL in the brainstem." (PMID 35941104, 2022). "Here, we sought to investigate the involvement of the GDF15 receptor GFRAL in the systemic metabolic adaptations and daytime-restricted anorexia upon muscle mitochondrial stress." (PMID 36271504, 2022). "One study suggested that the primary target for GDF15 is a distinct population of GFRAL/CCK neurons to engage the neural circuitry involved in anorexia and conditioned taste aversion." (PMID 34831213, 2021). "Mechanistically, induction of anorexia via the brainstem-restricted GDF-15 receptor GFRAL (glial cell-derived neurotrophic factor [GDNF] family receptor α-like) is well-documented." (PMID 32508832, 2020). "Furthermore, cancer-associated anorexia/cachexia syndrome has been linked to high circulating concentrations of GDF15, while blockade of GDF15 or its receptor, GFRAL, reduces anorexia and weight loss in rodents." (PMID 40530451, 2025). "Consequently, this challenges the notion that the circulating pleiotropic GDF15 exclusively activates GFRAL-expressing neurons in the AP/NTS, thereby being involved in anorexia and weight loss." (PMID 38474863, 2024). "GDF15 could acts as a critical mediator of anorexia-cachexia through the GDF15-mediated activation of hindbrain GFRAL-RET receptors." (PMID 35379793, 2022). "Furthermore, although total 24-h food intake remained unaffected, GFRAL signaling proved to be completely responsible for daytime-restricted anorexia elicited by GDF15." (PMID 36271504, 2022). "If this is the case, then either GFRAL neutralising antibodies or GFRAL antagonists may provide a possible co-treatment opportunity for patients suffering with cancer-related anorexia/cachexia." (PMID 32723474, 2020). "Interestingly, an earlier study from the same group has shown that switching to a fasting metabolism (which should be a consequence of GDF-15/GFRAL/RET-induced anorexia) can be life-saving in LPS- or Listeria-induced experimental sepsis." (PMID 32508832, 2020). "GFRAL was recently identified as a type of central nervous system receptor for mediating the anorectic actions of GDF-15, which could cause anorexia and weight loss in mice." (PMID 33201838, 2020). "Thus, we propose that the primary target for GDF15 is a distinct population of GFRAL/CCK neurons which span the AP/NTS to engage well-characterised circuitry involved in anorexia and conditioned aversion." (PMID 32723474, 2020). "The unique action of GDF15 on GFRAL at area postrema/nucleus tractus solitarii (AP/NTS) neurons is suggested to activate neurons in the parabrachial nucleus (PBN)-central amygdala circuit to mediate food and taste aversion, GDF15 driven anorexia and weight loss." (PMID 38474863, 2024).
Anorexia (continued). "GFRAL is exclusively expressed in the human brain stem and is responsible for GDF-15 mediated anorexia." (PMID 32508832, 2020). "Critically, blocking GFRAL (GDF15 receptor) alleviated anorexia without preventing muscle loss, whereas ActRIIB (GDF11 receptor) inhibition prevented atrophy and improved anorexia." (PMID 40969368, 2025). "It has also been found that GFRAL is localized on cholecystokinin (CCK) positive neurons; GDF15 activates CCK neurons, and GDF15-induced anorexia is attenuated by CCK signaling blockade, suggesting that GDF15 is mediated by anorexigenic signaling in CCK neurons in the brainstem." (PMID 39050134, 2024). "Using a mouse model with muscle-specific mitochondrial dysfunction, we here show that GFRAL is required for activation of systemic energy metabolism via daytime-restricted anorexia but not responsible for muscle wasting." (PMID 36271504, 2022). "However, anorexia and cachexia that should be caused by GDF-15-dependent activation of GFRAL are typically not observed during pregnancy, despite highly elevated GDF-15 serum levels." (PMID 32508832, 2020).
Cachexia (23 papers, 2018 to 2025). Severe weight loss, wasting of muscle, loss of appetite, and general debility related to a chronic disease. "Further, antibody mediated antagonization of GFRAL mitigated weight loss and preserved muscle mass in cancer cachexia mouse models with high‐circulating GDF‐15." (PMID 36642986, 2023). "One possible explanation for a worse survival of GDF15+GFRAL+RET-coexpressing GC patients could be cancer-associated cachexia." (PMID 34149933, 2021). "Circulating GDF15 and expression of GDF15 in tumour tissue have been shown to increase cancer related cachexia and novel data has shown GFRAL antagonism can reverse cachexia in mice." (PMID 40019842, 2025). "In summary, GDF-15/GFRAL antagonism may offer multiple therapeutic benefits, including anti-cachexia effects, potential relief of CINV, and enhanced immunotherapy." (PMID 41294666, 2025). "Through the activation of the GFRAL (GDNF-family receptor α-like)-RET (Rearranged during Transfection) signaling pathway, GDF15 can induce weight loss, making it a potential target for treating cachexia." (PMID 39172988, 2024). "The recent discovery of GFRAL in the hindbrain may explain the role GDF15 in the loss of muscle mass noted in patients with COPD, probably mediated though cachexia, similar to cancer patients." (PMID 33344478, 2020). "However, the recent use of monoclonal antibodies inhibiting GFRAL signaling reversed the GDF15-induced cachexia even under calorie-restricted conditions, revealing that GDF15 may lead to decreased adipose and muscle mass and function independently of anorexia." (PMID 33344478, 2020). "Novel research in the creation of GFRAL antagonists, thus inhibiting GFRAL dependent GDF15 response, have shown promise in reducing cachexia in in vivo models." (PMID 40019842, 2025). "Thereby, the GDF15/GFRAL/RET signaling pathway represents a potential therapeutic target for eating disorders, metabolic diseases and cancer-related cachexia." (PMID 38474863, 2024).